MIR6511A2 (microRNA 6511a-2)
Synonyms: hsa-mir-6511a-2; MIR6511A-2
Gene: MicroRNA gene on chromosome 16 (16,324,588 to 16,324,654, forward strand). Ensembl gene ENSG00000278221.
Homologues: Paralogues in human: MIR6511A1 (100% identical), MIR6511A3 (100% identical), MIR6511A4 (100% identical).